MDM2 (MDM2 proto-oncogene)
Diseases named in the same sentence as MDM2 in open-access papers (continued):
Sharing a sentence is not in itself a finding about the gene and the disease.
idiopathic pulmonary arterial hypertension (1 paper, 2023). A sporadic form of pulmonary arterial hypertension (PAH) characterized by elevated pulmonary arterial resistance leading to right heart failure. "Importantly, this ACE2-K788 site has already been identified as a target of the E3-ligase MDM2 in patients suffering from idiopathic pulmonary arterial hypertension." (PMID 37632105, 2023).
idiopathic retroperitoneal fibrosis (1 paper, 2025). "The results revealed that the false positivity rates of MDM2 IHC for fibroinflammatory diseases (sclerosing mesenteritis and retroperitoneal fibrosis) were 21% (3/14) and 10% (1/10), respectively." (PMID 40308488, 2025).
influenza infection (1 paper, 2017). "Two members of the top-ranked module, MDM2 and DOCK5, are most connected across all 12 co-expression networks and they were predicted to be the top drivers of the gene networks and potential host factors for influenza infection." (PMID 29214055, 2017).
Inguinal hernia (1 paper, 2025). Protrusion of the contents of the abdominal cavity through the inguinal canal. "Only one out of 43 (2.3%) cases demonstrated a positive MDM2 amplification result, thus labeling it as an incidental WDLS (11 cm) in the setting of an inguinal hernia repair for which the patient required a subsequent orchiectomy." (PMID 40799874, 2025).
intraepithelial neoplasia (1 paper, 2020). A precancerous neoplastic process that affects the squamous, glandular, or transitional cell epithelium without evidence of invasion. "Based on our predictions, combinatorial targeting of Mdm2 and JAK is also efficacious in the intraepithelial neoplasia, while targeting Mdm2 in combination with IKKs is more efficacious in the liver metastasis." (PMID 32073727, 2020).
intrahepatic cholangiocarcinoma (1 paper, 2024). A carcinoma that arises from the intrahepatic bile duct epithelium in any site of the intrahepatic biliary tree.
latent infection (1 paper, 2016). "The upregulation of transcripts of BBC3, GADD45A, MDM2, TP53I3, and downregulation of HEXIM1 during latent infection was confirmed as significant by RT-qPCR." (PMID 27898737, 2016).
lentivirus infection (1 paper, 2017). Virus diseases caused by the Lentivirus genus. "We genetically down‐regulated the expression of MDM2 in podocytes by lentivirus infection and examined the impact on podocyte cell cycle." (PMID 28643424, 2017).
liver failure (1 paper, 2023). A liver disease characterized by the liver losing or has lost all of its function. "To better understand the influence of MDM2 in the liver failure process, we first detected the expression changes of MDM2 in the liver tissues of ALF mice by RT‐qPCR and western blot analysis, and it suggested that MDM2 was high‐expressed." (PMID 36840487, 2023).
liver neoplasm (1 paper, 1999). Tumors or cancers of the LIVER. "Therefore, the RT-PCR assays for GAGE-1, -2 and MDM2 might be useful adjuncts in cytodiagnosis of liver neoplasms." (PMID 10389981, 1999).
lysosomal storage disorders (1 paper, 2024). "P4 antagonized this process by inducing lysosomal storage disorders and promoting the proteasomal degradation of TRPML1 via murine double minute 2 (MDM2)-mediated polyubiquitination." (PMID 38295116, 2024).
macular holes (1 paper, 2022). A hole in the macula of the retina. "In brief, EMMs and ILMs from EMM cases with preoperative macular holes tended to exhibit somatic mutation at the MDM2 T309G locus." (PMID 35359434, 2022). "Association of somatic mutation at the MDM2 T309G locus and macular holes in EMM cases." (PMID 35359434, 2022). "Moreover, EMMs and ILMs, especially those complicated with macular holes, are genetically unstable at the MDM2 T309G locus." (PMID 35359434, 2022). "In addition, EMMs and ILMs are genetically unstable at the MDM2 T309G locus, especially when complicated with preoperative macular holes." (PMID 35359434, 2022). "Furthermore, EMMs (p = 0.0053; OR = 8.250) and EMM-ILMs (p = 0.0233; OR = 14.40) from patients with preoperative macular holes were more predisposed toward somatic mutations at the MDM2 T309G locus than those from patients without preoperative macular holes." (PMID 35359434, 2022).
malignant lipomatous tumors (1 paper, 2015). "Using FISH, the absence of DDIT3 alteration or MDM2 amplification was indicated in the present case, thus differentiating the benign DFML from malignant lipomatous tumors." (PMID 25621027, 2015).
Multiple Organ Failure (1 paper, 2025). A progressive condition usually characterized by combined failure of several organs such as the lungs, liver, kidney, along with some clotting mechanisms, usually postinjury or postoperative. "To exclude the possibility of multiple-organ failure, we conducted blood assessments of liver function markers, albumin (ALB) and alanine aminotransferase (ALT), in control versus Mdm2-cKO mice, showing no significant changes." (PMID 39946208, 2025).
myxoma (1 paper, 2025). A benign soft tissue neoplasm characterized by the presence of spindle and stellate cells, lobulated growth pattern, and myxoid stroma formation. "Herein, we report a diagnostically challenging case of retroperitoneal/psoas muscle WDLPS with extensive myxoid stroma, absence of macroscopic fat, and negative MDM2 gene amplification, which closely mimicked an intramuscular myxoma on both imaging and biopsy." (PMID 40677885, 2025). "This case highlights a rare presentation of MDM2-negative WDLPS with extensive myxoid stroma, masquerading as an intramuscular myxoma both radiologically and histologically." (PMID 40677885, 2025).
Nephropathy (1 paper, 2019). A nonspecific term referring to disease or damage of the kidneys. "To confirm this hypothesis, we induced nephropathy in vivo or tubular‐cell death in vitro with cisplatin and analyzed the effects of MDM2 inhibitor on this toxicity and on NFκB signaling." (PMID 30564368, 2019).
nerve sheath tumors (1 paper, 2013).
Neurodegeneration (1 paper, 2016). Progressive loss of neural cells and tissue. "Other than the potential candidate genes, the compact SPNW also included many significant connecting proteins like APP, BACE1, CCNA2, CREB1, E2F1, EGR1 and MDM2 which were previously implicated to play critical roles in many neurodegeneration disease pathogenesis including Alzheimer’s." (PMID 26784894, 2016).
neuroendocrine tumors (1 paper, 2020). "Sustained ectopic MYCN expression may suffice to induce oncogenic transformation in this setting, whereas MDM2-mediated positive feedback, to further upregulate MYCN translation, is needed for development of intrinsically MYCN-driven neural and neuroendocrine tumors." (PMID 33425720, 2020).
non-cutaneous melanoma (1 paper, 2019). Melanoma is a malignant tumor of melanocytes, cells that are derived from the neural crest. "From a cross-check of the DE analysis, we found that the MDM2 proto-oncogene, shown to be recurrently gained in human non-cutaneous melanomas, was almost four times more highly expressed in canine oral melanoma tumors than in controls (lFC = 1.96; padj = 0.02)." (PMID 31234577, 2019).
Onset (1 paper, 2024). The age group in which disease manifestations appear. "Early-onset cancer incidence in LFS has been associated with excessive telomere shortening due to MDM2 signaling disturbances that promote genomic instability and increase cancer susceptibility, highlighting it as an important therapeutic target." (PMID 39519030, 2024).
ovarian liposarcoma (1 paper, 2025). "Primary ovarian liposarcoma is extremely rare in clinical practice and is typically diagnosed through lesion biopsy or postoperative pathology combined with immunohistochemistry and FISH results (e.g., MDM2 positive, CD4 positive, etc.)." (PMID 41450911, 2025).
pancreatic adenocarcinoma (1 paper, 2017). "In summary, MDM2 expression is associated with poor prognosis and progression after gemcitabine-based chemotherapy in advanced pancreatic adenocarcinoma." (PMID 28678832, 2017). "Downregulation and induction of the autoubiquitination of MDM2 with SP141 inhibit pancreatic adenocarcinoma both in vitro and in vivo." (PMID 28678832, 2017). "Therefore, MDM2 amplification was not the major mechanism of MDM2 expression in our patient population, which aligns with previous studies reporting rare MDM2 amplification in pancreatic adenocarcinoma." (PMID 28678832, 2017).
papilloma (1 paper, 2020). A benign epithelial neoplasm that projects above the surrounding epithelial surface and consists of villous or arborescent outgrowths of fibrovascular stroma. "The EBNA1-mediated activation of E2F1 via MDM2 differs from other oncogenic viruses such as Simian, Human papilloma and Adeno that via Large T, E6 and E1A, respectively, compete with E2F1 for the binding to the retinoblastoma protein (pRb)." (PMID 32453417, 2020).
parathyroid adenoma (1 paper, 2006). "One study revealed that 76% of the patients with typical parathyroid adenoma had a phenotype of p27(+)bcl-2(-)Ki-67(-)mdm2(+) compared to none of those patients diagnosed with PC." (PMID 16504029, 2006).
parathyroid carcinoma (1 paper, 2021).
periodontitis (1 paper, 2022). An acute or chronic inflammatory process that affects the tissues that surround and support the teeth. "The genes with the highest degrees in shared-DEminRNA-gene network included PTEN, CCND1, MDM2, SCD, and TNRC6A, and these may be important miRNA-deregulated mediators linking H. pylori infection and periodontitis." (PMID 35132337, 2022).
Pleural effusion (1 paper, 2025). The presence of an excessive amount of fluid in the pleural cavity. "For pleural effusion, BL and EP tumor cells had higher expression of mitochondria-associated genes, such as CO (cytochrome C oxidase), ND (NADH dehydrogenase), and ATP6, while LP cells expressed EMT-associated genes, such as YEATS4, MDM2, and RGS5." (PMID 39955556, 2025).
plexiform ameloblastoma (1 paper, 2015). A histologic variant of solid/multicystic ameloblastoma characterized by the presence of basal cells forming anastomosing strands and cords in a delicate stroma. "Only 3 (10.7%) cases expressed MDM2, all showing weak immunoreactivity; two of them were males with plexiform ameloblastoma while the third case was a female with cystic ameloblastoma." (PMID 27386018, 2015).
polycystic ovarian syndrome (1 paper, 2023). "Previous studies have shown a close association of MDM2 rs2279744 T > G with the human polycystic ovarian syndrome and human reproduction." (PMID 37648962, 2023).
polycythemia vera (1 paper, 2020). "MDM2 inhibition has also been shown to enhance apoptosis of polycythemia vera (PV) progenitor cells." (PMID 32823910, 2020).
Premature ovarian insufficiency (1 paper, 2024). Amenorrhea due to loss of ovarian function before the age of 40.
promyelocytic leukemia (1 paper, 2014).
pulmonary blastoma (1 paper, 2012). A malignant neoplasm of the lung composed of tubular structures and immature mesenchymal elements, which may differentiate towards skeletal and smooth muscle, cartilage or a combination of muscle and cartilage. "From our findings we conclude that similar to pulmonary blastoma pulmonary carcinosarcoma may harbour MDM2 and lack EGFR mutations." (PMID 23006472, 2012). "Over-expression of MDM2 has previously been observed in 83% of biphasic pulmonary blastomas, but it has so far not been studied in pulmonary carcinosarcomas." (PMID 23006472, 2012).
rectal carcinoma (1 paper, 2017). A malignant epithelial neoplasm that arises from the rectum and invades through the muscularis mucosa into the submucosa.
Renal neoplasm (1 paper, 2025). The presence of a neoplasm of the kidney. "Immunohistochemical staining with markers such as p16 and MDM2 helps differentiate DDLPS from other renal neoplasms." (PMID 40918771, 2025).
retinal cancer (1 paper, 2025). A malignant neoplasm involving the retina.
retinal detachment (1 paper, 2023). An eye emergency condition which may lead to blindness if left untreated.
sarcomatoid carcinoma (1 paper, 2018). A malignant epithelial neoplasm characterized by the presence of spindle cells and anaplastic morphologic features. "As other immunohistochemical markers were negative, including CD45, CD163, CD68, Desmin, Myogenin, Melanoma, S100, α-SMA, Cytokeratin 7, Cytokeratin 20, MDM2 and CDK4, the tumors were diagnosed as sarcomatoid carcinomas." (PMID 29874846, 2018).
schwannoma (1 paper, 2023). A benign, usually encapsulated slow growing tumor composed of Schwann cells.
spinal muscular atrophy (1 paper, 2022). A motor neuron disease that affect the muscles, and characterized by muscle weakness and atrophy resulting from progressive degeneration and irreversible loss of the anterior horn cells in the spinal cord (i.e., lower motor neurons) and the brain stem nuclei.
spindle cell liposarcoma (1 paper, 2025). A morphologic variant of well differentiated liposarcoma characterized by the presence of bland spindle cells and lipoblasts within a myxoid or fibrous stroma. "Thorough pathologic evaluation is required for a definitive diagnosis of spindle cell liposarcoma, including the characteristic CD34 and MDM2 expression." (PMID 41141132, 2025).
squamous cell carcinoma of oropharynx (1 paper, 2017). "Functional mouse double minute-2 (MDM2) promoter variants may alter MDM2 expression and thus affect radiotherapy response and prognosis of squamous cell carcinoma of oropharynx (SCCOP)." (PMID 28045062, 2017).
squamous cell carcinoma of the vulva (1 paper, 1999).
T cell lymphoma (1 paper, 2024).
T-cell leukemia (1 paper, 2022). A malignant disease of the T-lymphocytes in the bone marrow, thymus, and/or blood. "In adult T-cell leukemia, aberrantly expressed FOSL2 has been demonstrated to induce CCR4 expression MDM2." (PMID 36092920, 2022).
tauopathy (1 paper, 2023). Neurodegenerative disorders involving deposition of abnormal tau protein isoforms (tau proteins) in neurons and glial cells in the brain. "Sections derived from the same tauopathy brains revealed a double immune reactivity of Tau lesions with MDM2, similarly to what found for AT8, but not with Aβ-peptide senile plaques." (PMID 37353565, 2023).
temporal lobe epilepsy (1 paper, 2025). A localization-related (focal) form of epilepsy characterized by recurrent seizures that arise from foci within the temporal lobe, most commonly from its mesial aspect.
thyroid sarcoma (1 paper, 2022). A malignant soft tissue neoplasm primarily involving the thyroid gland. "Histological exam diagnosed a rare case of primary thyroid sarcoma with diffuse and strong expression of mouse double minute 2 homolog (MDM2) oncoprotein." (PMID 34984625, 2022).
thyroid tumor (1 paper, 2022). A benign or malignant neoplasm affecting the thyroid gland. "Thus, we decided to analyze whether there was an association between p90RSK activation (anti-pRSK) and MDM2 expression levels in primary thyroid tumors." (PMID 36612117, 2022). "For this purpose, we performed immunostaining for pRSK and MDM2 protein in 13 thyroid tumors (9 PTC, 2 FTC and 2 ATC)." (PMID 36612117, 2022). "Finally, even if on a small number of samples, we demonstrated the existence of a correlation between p90RSK activation and MDM2 phosphorylation in primary thyroid tumors." (PMID 36612117, 2022). "Finally, an immunohistochemistry evaluation of primary thyroid tumors, in which p90RSK is very active, confirms MDM2 stabilization mediated by p90RSK phosphorylation." (PMID 36612117, 2022).
tooth agenesis (1 paper, 2020). A tooth disease characterized by failure to develop one or more missing teeth.
vitiligo (1 paper, 2021). Generalized well circumscribed patches of leukoderma that are generally distributed over symmetric body locations and is due to autoimmune destruction of melanocytes.
vulvar carcinoma (1 paper, 1999).